CD4 (CD4 molecule)
Diseases named in the same sentence as CD4 in open-access papers (continued):
Sharing a sentence is not in itself a finding about the gene and the disease.
Peritoneal Fibrosis (4 papers, 2014 to 2023). Disorder characterized by a wide range of structural changes in PERITONEUM, resulting from fibrogenic or inflammatory processes. "Examination of effector CD4+ T cells during the period associated with the development of peritoneal fibrosis (days 28–49) showed that this Th1 cell phenotype was maintained and represented the most prominent CD4+ T cell population within the peritoneal cavity." (PMID 24412616, 2014). "In a mouse model of peritoneal fibrosis, PARI reduced peritoneal inflammation and fibrosis through the activation of CD4+ and CD8+ Tregs in the peritoneal cavity." (PMID 29085356, 2017). "Transfer of Th1 cells, but not naive CD4+ T cells, induced peritoneal fibrosis in Il6−/− mice." (PMID 24412616, 2014).
pneumothorax (4 papers, 2019 to 2024). Abnormal presence of air in the pleural cavity. "On the other hand, HIV patients with current or previous PCP and pneumothorax had CD4 < 100 cells/μL, and 58% of them had CD4 < 50 cells/μL." (PMID 30658592, 2019). "In PBC, it is uncertain but possible that the characteristic CD4 and activated alveolar macrophages predominating inflammatory infiltration would exaggerate pneumatocele wall thinning, which is conducive to pneumothorax." (PMID 30658592, 2019). "Our patient’s presentation with a pneumothorax, along with the discovery of HIV infection and critically low CD4 counts, exemplifies the potential complexity and severity of this infection even in industrialized settings where the incidence is low." (PMID 38899257, 2024).
polio (4 papers, 2021 to 2025). "As this was our first use of an AIM-based method to detect Ag-specific T cell responses to polio vaccines, we wanted to first investigate the prevalence, frequency, and overlap of polio Afumg-specific CD4+ and CD8+ T cells in our sample set." (PMID 40661308, 2025).
primary effusion lymphoma (4 papers, 2012 to 2022). A large B-cell lymphoma located in the body cavities, characterized by pleural, peritoneal, and pericardial fluid lymphomatous effusions and that is always associated with human herpes virus-8 (HHV-8). "Primary effusion lymphoma (PEL) is a variant of DLBCL primarily seen in the immunosuppressed with high HIV viral loads and low CD4+ T-cell counts." (PMID 33573146, 2021).
proctitis (4 papers, 2018 to 2025). An inflammatory process affecting the anus. "Discussion: This is among the first reported cases of syphilitic proctitis in a patient with CD4 < 50 cells/μL, where advanced immunophenotyping differentiated syphilitic inflammation from neoplastic or inflammatory mimics." (PMID 40700331, 2025). "We describe an unusually severe case of syphilitic proctitis in the setting of advanced HIV-related immunosuppression (CD4 39 cells/μL), in which targeted immunophenotyping (ERG and CD38) was a valuable adjunctive tool in the differential diagnosis." (PMID 40700331, 2025). "MAI infection should be suspected as possible etiology for proctitis in HIV positive patient with low CD4 count, as proctitis, though infrequent can be the sole presentation for disseminated MAI infection in patients with HIV and low CD4 count." (PMID 31885949, 2019). "We present a rare case of a patient with HIV and low CD4 count presenting with proctitis as manifestation of disseminated MAI infection." (PMID 31885949, 2019). "We found that in UC patients with proctitis and left-sided colitis the proportion of LP CD3+CD4+Foxp3+ Tregs was significantly higher in inflamed tissue than uninvolved tissue." (PMID 30425718, 2018).
pulmonary fungal infection (4 papers, 2015 to 2024). "It has been shown that in response to pulmonary fungal infection, naïve CD4+ T cells differentiate into diverse helper subsets that are distinguished by their cytokine profiles." (PMID 39324785, 2024). "In previous studies, we determined that CCR2+ monocytes are required to facilitate the activation of CD4+ T cell responses during pulmonary fungal infection." (PMID 39324785, 2024). "In previous studies, we observed that CCR2+ Ly6C+ monocytes are important precursors of mo-DCs that orchestrate the development of Th1 CD4+ T cell responses to pulmonary fungal infection." (PMID 29317510, 2018). "Since these DC are the main coordinators of antigen presentation to CD4+ T cells, the close proximity of chitin degradation and recognition likely allows the DC to efficiently influence the fate of CD4+ T cells during pulmonary fungal infection." (PMID 25764512, 2015). "Similarly, recently published data demonstrate that the gut microbiota regulates Th17 CD4 T-cell polarization during pulmonary fungal infections." (PMID 28604843, 2017). "To investigate Th2 cell responses to pulmonary fungal infection, we developed a peptide-MHCII tetramer to track antigen-specific CD4+ T cells produced in response to infection with the fungal pathogen Cryptococcus neoformans." (PMID 25764512, 2015).
rectal tumor (4 papers, 2019 to 2023). "Furthermore, we constructed a tissue microarray on colon or rectal tumor tissues containing a large cohort of CRC patients (n = 302) and detected the expression of IGSF6, CD4+ and CD8+ T cell with multiple immunofluorescences." (PMID 37989761, 2023).
rhinosinusitis (4 papers, 2009 to 2022). "The improved immunity of the HIV infected women as evidenced by a higher level of mean latest CD4 cell count compared to the Nadir CD4 cell count would have reduced the possibility of opportunistic rhinosinusitis in them." (PMID 27047688, 2016). "Thus, the purpose of this study was to assess changes in the prevalence and pattern of rhinosinusitis and CD4+ lymphocyte serum counts in a specific population of Brazilian HIV-infected children following the introduction of HAART." (PMID 19488563, 2009).
Sensory neuropathy (4 papers, 2019 to 2023). Peripheral neuropathy affecting the sensory nerves. "Collectively, these findings uncover a central role for complement in CD4 T cell-dependent corneal nerve damage in multiple disease settings and indicate the possibility for complement-targeted therapeutics to mitigate sensory neuropathies." (PMID 31414985, 2019).
Skin ulcer (4 papers, 2015 to 2025). A discontinuity of the skin exhibiting complete loss of the epidermis and often portions of the dermis and even subcutaneous fat. "With the increase in time, skin ulcers and urinary system infection were significantly improved, levels of CD4+, CD4+/CD8+ ratio, and DP lymphocytes increased, and levels of SLE‐related indicators all decreased in the 1,25(OH)2D3 group." (PMID 28063200, 2017). "Although grade 3 injection site reactions are not desirable, the biopsy of the injection site with the infiltrate of CD4+ and CD8+ T cells suggest that these skin ulcerations are “on target” toxicities." (PMID 26405584, 2015). "Similarly, CL recovered patients displayed increased TCM and diminished TEM and TTE CD4+CCR4+ and CD8+CCR4+ cells compared with patients with skin ulcers." (PMID 40277930, 2025).
Sm (4 papers, 2018 to 2020). "CD4+ Foxp3+ Treg cells expressed IL-4Rα under a steady state and up-regulated their expression upon Sm infection." (PMID 30379806, 2018). "Thus, a significant increase of naïve CD4+ T cells was found in patients with SM, while a generalized decrease of virtually all blood CD4+ T-cell subsets was found in CVID, with normal values among MBL subjects." (PMID 32174910, 2020). "Thus, a significant increase of circulating naïve CD4+ T cells was found in SM, while patients with CVID showed a significant decrease of all CD4+ T-cell subsets, except TFH cells, when compared to age-matched controls." (PMID 32174910, 2020).
status epilepticus (4 papers, 2014 to 2023). Status epilepticus is defined as a continuous seizure lasting more than 30 min, or two or more seizures without full recovery of consciousness between any of them. "Another study reported that CD4+ T cells were observed 96 h after status epilepticus." (PMID 37435496, 2023). "Furthermore, CD3+ cells with a CD4+ phenotype were observed after status epilepticus induced by a single, but higher dose of pilocarpine probably leading to a more pronounced blood-brain barrier disruption that could be responsible for the early presence of CD3+ cells in the hippocampus." (PMID 29182639, 2017). "Uptake of labeled S100B by rat spleen CD4+ or CD8+ and CD86+ dendritic cells was exacerbated by pilocarpine-induced status epilepticus which is accompanied by BBBD." (PMID 24988410, 2014).
Thrombocytosis (4 papers, 2020 to 2025). Increased numbers of platelets in the peripheral blood. "Additionally, it may possibly be associated with polyclonal hypergammaglobulinemia, reversal of CD4/CD8 ratio, the elevated erythrocyte sedimentation rate (ESR), microcytic anemia, and thrombocytosis." (PMID 37388202, 2023).
tongue SCC (4 papers, 2017 to 2022). "In contrary, IL-4-producing CD4+ T cells was higher in advanced stages and in tongue SCC patients with larger tumor size which are linked to a poor prognosis." (PMID 36376825, 2022). "But, in stage IV, the percentage of CD4+ T cells was significantly higher in TDLNs of patients with tongue SCC compared to those with laryngeal SCC (P = 0.025)." (PMID 36376825, 2022). "A positive correlation between PD-L1 expression and CD8+ and CD4+ TILs was found in tongue SCC, with higher CD4+ PD-1+ TILs compared to CD8+PD-1+ TILs." (PMID 32708945, 2020). "In addition, in patients with tongue SCC, the frequency of CD4+CD25+Foxp3+CD127low/− cells was significantly lower in TDLNs of LN+ patients (patients with at least one involved LN) in comparison with LN– ones (patients without involved LN, P = 0.036)." (PMID 36376825, 2022). "Moreover, IL-10 facilitates cross talk between CD19+IL-10+ Bregs and CD4+CD25− T cells in tongue squamous cell carcinoma patients, resulting in the conversion of these resting T cells into Tregs." (PMID 28261223, 2017). "In tongue SCC, the gMFI of IFN-γ production in CD4+T cells was significantly higher in TDLNs of patients with lymphatic/vascular invasion (P = 0.015)." (PMID 36376825, 2022). "In this study, we assessed the role of TIL markers (CD3, CD4, CD8, and FOXP3) in a large cohort of patients with pure tongue squamous cell carcinoma receiving maximal curative treatment involving radical surgery and adjuvant RT or adjuvant CCRT." (PMID 30153850, 2018). "Our study demonstrated that in tongue squamous cell carcinoma, higher CD4 infiltration and higher CD4/CD3, CD4/CD8, and CD4/FOXP3 ratios were associated with the absence of LVI, indicating the role of CD4 TILs in the prevention of early metastatic invasion." (PMID 30153850, 2018). "In addition, the frequency of CD4+IFN-γ+TNF-α+ T cells showed a non-significant increasing trend in TDLNs of laryngeal compared with tongue SCC (P = 0.086)." (PMID 36376825, 2022).
tongue tumors (4 papers, 2019 to 2025). "Furthermore, we observed that supplementing α-PD-1 + α-CTLA-4 treatment with STING agonist administration into the flank tumors was associated with a decrease in the frequencies of CD4+Foxp3+ Treg as well as of MDSC expressing Arginase 1 in both flank and tongue tumors." (PMID 31533840, 2019). "The data showed that SP2509 treatment promoted the infiltration of CD45+, TCRβ+, CD4+, and CD8+ T cells in tongue tumors." (PMID 40246812, 2025). "Among the OSCC locations, floor of the mouth tumors were more likely to CD4- and tumors of the tongue were more likely to express higher levels of T cell markers (especially CD3 and CD4) compared to the other oral cavity subsites." (PMID 35957892, 2022). "When combined EGFR and CD4 expression was analyzed, it was found that EGFR+/CD4+ expression was associated with never smokers (p=0.03), tongue tumor disease site (p=0.03), T1 tumors (p=0.02), N0 tumors (p=0.002), no LVI (p=0.02) and no BI (p=0.01)." (PMID 35957892, 2022). "Nevertheless, our findings support prior work which found that most of tongue tumors are “TIL-high”, the TILs were associated with absence of LVI and were likely CD4+ T cells." (PMID 35957892, 2022).
trypanosomiasis (4 papers, 2011 to 2025). Infection with protozoa of the genus trypanosoma. "Having demonstrating that IL-27 is crucial for dampening trypanosomiasis-associated CD4+ T cell activation, needed for prolonged survival, we next addressed the mechanism of CD4+ T cell-mediated mortality of infected IL-27R-/- mice." (PMID 26222157, 2015).
vaginal candidiasis (4 papers, 2008 to 2022). "The prevalence of vaginal candidiasis in HIV-infected women depends on the CD4 count." (PMID 18598359, 2008). "The findings were evaluated in correlation with CD4 cell counts, HIV viral load, age at first sexual intercourse, number of sexual partners, vaginal candidiasis, and Gardnerella using statistical methods." (PMID 35744023, 2022).
venous thromboembolism (4 papers, 2020 to 2022). Occlusion of the lumen of a vein by a thrombus that has migrated from a distal site via the blood stream. "Furthermore, there was an increased risk of PE in patients with previous episodes of venous thromboembolism, a reduced blood ratio between CD4 and CD8 lymphocytes and antiphospholipid antibody positivity." (PMID 34199396, 2021). "Summary of the CD4 and viral load results obtained for patients with venous thromboembolism in this study." (PMID 35399748, 2022).
vitamin B12 deficiency (4 papers, 2013 to 2025). A disease characterized by low serum levels of vitamin B12, either inherited or acquired. "This study aimed to determine the prevalence of vitamin B12 deficiency, identify associated factors, and examine its correlation with CD4 count among HIV-positive adults." (PMID 41024214, 2025). "An inverse correlation between CD4 counts and vitamin B12 deficiency was also observed (Spearman’s rho = − 0.24; p < 0.001)." (PMID 41024214, 2025). "This study aimed to determine vitamin B12 deficiency prevalence, identify associated factors, and assess correlation with CD4 counts among HIV-positive adults attending Kayunga Regional Referral Hospital (KRRH), Central Uganda." (PMID 41024214, 2025). "Compared with healthy individuals, the proportions of CD4+ lymphocytes were significantly higher in patients with vitamin B12 deficiency, resulting in an abnormally high CD4+/CD8+ ratio." (PMID 35056870, 2022). "On the other hand, some authors observed reductions of cytotoxic cells and an increase in the CD4/CD8 ratio following folate and vitamin B12 deficiency." (PMID 24288024, 2013). "Lack of meat in diet results in vitamin B12 deficiency which causes impaired immune system activity such as decreased lymphocyte especially CD8, natural killer cells, lymphokine activated killer cells and an increase in the CD4/CD8 ratio." (PMID 36201533, 2022).
xerosis (4 papers, 2009 to 2022). "Both groups showed mild xerosis of grafts with intact skin anatomy, and distinct effects of β2‐agonist treatment were lost in the CD4+ and CD8+ memory T cell, Th1 and Treg populations 7 days after VCA." (PMID 35994413, 2022).
Yersinia infection (4 papers, 2010 to 2025). "In fact, CD8 or CD4 T-cell induction by Yersinia infection is supported by the same mouse model." (PMID 24468017, 2014). "Interestingly, the Yersinia infection significantly reduced the proliferation of the OVA-specific CD4+ T cells co-cultured with OVA protein (p = 0.0047) or peptide-pulsed (p = 0.037) CD8α+ DCs." (PMID 21124820, 2010). "Many studies have shown that cells of the innate immunity like macrophages and neutrophils, and adaptive immunity like CD4+ Th1 and CD8+ T cells are crucial in the control of Yersinia infections." (PMID 25075520, 2014).
acute lung injury (3 papers, 2019 to 2025). A condition of lung damage that is characterized by bilateral pulmonary infiltrates (pulmonary edema) rich in neutrophils, and in the absence of clinical heart failure. "Study showed that CD4+CD25+FoxP3+ Treg is a critical effector to protect against transfusion-related acute lung injury (TRALI)." (PMID 32565732, 2020).
acute retinal necrosis (3 papers, 2014 to 2020). "Necrotizing retinopathy caused by VZV can present as acute retinal necrosis (ARN) or progressive outer retinal necrosis (PORN) in immunocompetent and immunocompromised patients but PORN occurs almost exclusively in HIV-seropositive patients with CD4 cell count < 100 cells/uL." (PMID 26740936, 2015).
adrenocortical carcinoma (3 papers, 2023 to 2024). "In particular, in adrenocortical carcinoma, GC excess is significantly associated with CD3+CD4+ T cell depletion, and patients with GC excess and low TILs had a particularly poor overall survival compared to those with normal GC levels and high TILs (27 vs 121 months)." (PMID 37114049, 2023). "As an exception to the rule, adrenocortical carcinoma samples displayed negative correlations between CXCR4 expression and levels of infiltrating CD4+ and CD8+ T cells as well as PD-L1." (PMID 36672341, 2023).
Aicardi-Goutières Syndrome (3 papers, 2012 to 2015). "Supporting this conclusion, the authors also demonstrated that a mutation in SAMHD1 in cells from a patient with Aicardi-Goutiere's syndrome renders resting CD4+ T cells permissive to HIV infection." (PMID 24404168, 2014). "The Aicardi-Goutières syndrome (AGS)-related anti-retroviral protein SAM domain and HD domain 1 protein (SAMHD1) inhibits retroviruses in non-dividing myeloid cells and resting CD4+ T cells by depleting dNTP levels." (PMID 26001115, 2015).
alcoholic cirrhosis (3 papers, 2013 to 2021). "In this study, we report higher frequencies of circulating IL-22-producing CD4+CD45RO+ T cells in AH patients than in alcoholic cirrhosis patients and healthy controls." (PMID 23372820, 2013). "We measured the percentages of CD4+CD45RO+ T cells that produced IL-22 in the peripheral blood at baseline and detected a 1.7-fold increase in the frequency of these cells in AH patients compared with both alcoholic cirrhosis patients and healthy controls." (PMID 23372820, 2013). "Our further analysis indicated that the percentage of CD8+, CD4+, and CD4−CD8−(double negative, DN) cells among total MAIT cells were similar among patients with alcoholic cirrhosis, mixed cirrhosis, and HCs." (PMID 34321090, 2021).
alcoholic hepatitis (3 papers, 2019 to 2025). Acute hepatitis resulting from ingestion of alcohol. "The decreased number of peripheral blood CD4+/CD25+ T cell regulatory population is associated with immune activation in alcoholic hepatitis patients, as evidenced by increased inflammatory cytokines." (PMID 31244862, 2019). "For instance, in alcoholic hepatitis (AH), the distribution of CD4+CD25+CD127-/lo Tregs was analyzed using flow cytometry and was lower (p < 0.05) in patients with AH compared to healthy individuals." (PMID 40918132, 2025).
amenorrhea (3 papers, 2013 to 2025). The absence of menses in a woman who has achieved reproductive age. "Use of ART (HR: 0.48, 95% CI: 0.32–0.71, P = 0.003) and higher CD4 cell counts (P = 0.007) have been linked to a lower incidence of amenorrhea." (PMID 24454386, 2013). "A 2010 article noted that in WLWH in Nigeria, rates of amenorrhea, oligomenorrhea, and irregular bleeding were higher than in WLWH; these rates, increased with lower CD4 counts and lack of ART use." (PMID 41048894, 2025).
angioedema (3 papers, 2007 to 2025). Swelling involving the deep dermis, subcutaneous, or submucosal tissues, representing localized edema. "These triggers activate innate immunity, CD4 + lymphocytes, and the production of IL-1β, IFN-γ, and TNF-α, which subsequently induce cell damage and apoptosis, which are key mechanisms for the development of angioedema and/or urticaria." (PMID 34906225, 2021).